CD4 (CD4 molecule)
Diseases named in the same sentence as CD4 in open-access papers (continued):
Sharing a sentence is not in itself a finding about the gene and the disease.
HCMV infection (continued). "In the HEXA study, this would correspond to a finding of 21 individuals with an inverted CD4/CD8 ratio and since the prevalence of persistent CMV infection is 77 %, we would expect to find 16 of these 21 individuals to be CMV positive whereas five individuals would be CMV negative by random." (PMID 22415616, 2013). "The induction of NKG2D cell surface expression on HCMV-primed CD4+ T-cells was influenced by the HCMV serostatus of the donors, as NKG2D+ CD4+ T-cells were solely obtained from blood donors who had previously encountered HCMV infection." (PMID 22870231, 2012). "For instance, CMV infection promotes an increase in the number of CD8+ T cells and NK‐T cells, producing an immunostimulatory effect, while BK polyomavirus reactivation leads to a decrease in the number of CD4+ and CD8+ T cells, resulting in an immunosuppressive effect." (PMID 41321698, 2025). "Other variables, such as cytomegalovirus infection (not evaluated here), may influence the CD4/CD8 ratio reconstitution level in these individuals." (PMID 40969513, 2025). "However, the role of recently identified CD4+ T cell subsets, i.e., Th22 and Th9, against the HCMV infection, has not been evaluated yet." (PMID 37403036, 2023). "This modulation of the CD4+ T cell function also extends to HCMV-specific CD4+ T cells which have a regulatory cell phenotype or secrete cIL-10, and have been observed to play an important role in resolving the complications from HCMV infection in hematopoietic stem cell transplant patients." (PMID 36558866, 2022). "Indeed, primary and latent HCMV infection can be kept in check by the host immune system in a hierarchical and redundant way through type I and II interferons (IFNs), natural killer cells (NKs), and CD8+ and CD4+ T-cells." (PMID 33567734, 2021). "The same group also examined an adult allogeneic HSCT patient cohort, finding that the same cut-off level of 1 HCMV-specific CD4+ T-cell/μl of blood was able to identify patients who could spontaneously control HCMV infection in the absence of treatment." (PMID 32509591, 2020). "For thymus, HCMV infections and reactivations stimulated higher hCD45 cellularity and higher absolute numbers of CD4/CD8 double negative (DN, REAC vs. CTR p = 0.02), double positive (DP, n.s.), and CD4 single positive (CD4SP, INF vs. CTR p = 0.01, REAC vs. CTR p = 0.01) T cells." (PMID 30524448, 2018). "Furthermore, CD4+CD28null T cells were found to be present in patients with AAV in a higher percentage compared to controls and were found to be related to a previous CMV infection." (PMID 28084533, 2017). "In this study, a high throughput method was used to define the frequency of CD4+ and CD8+ T cells specific for four HCMV proteins in the naïve compartment of seronegative subjects and the effector/memory compartments of subjects with primary/remote HCMV infection." (PMID 29112951, 2017). "When comparing the impact of HCMV infection, in donors of all ages, on the numbers of differentiated T cell subsets [representative donor phenotype staining is shown], we observed a significant expansion of the effector memory (TEM—CD27−CD45RA−) population in both CD8+ and CD4+ T cells." (PMID 28694811, 2017). "Immune control of primary and latent HCMV infection is organized in a hierarchical but also redundant manner, with prominent roles for type I and type II interferons, NK cells, and CD8+ but also CD4+ T-cells, while antiviral antibodies are essential to restrict dissemination of recurrent virus." (PMID 24967373, 2014). "Group 3 included patients controlling HCMV infection with moderate levels of viral DNA and absence of specific CD4+ T cells at the beginning of follow-up, while group 4 included patients suffering from severe HCMV infection with very high viral load and, thus, requiring antiviral treatment." (PMID 25166270, 2014).
HCMV infection (continued). "Following primary HCMV infection a subpopulation of CD4 T cells emerges that is CD28 negative, expresses granzyme B, and maybe possesses cytotoxic capacities in renal transplant recipients." (PMID 23717308, 2013). "Importantly, the phenotypic composition of the Hobit− CD4+, CD8+, and γδ+ T cell population stably represented naïve and memory T cells throughout the sampling period, suggesting that the events in T cell differentiation during the course of hCMV infection are restricted to the Hobit+ cells." (PMID 28392788, 2017). "However, several patients with or without severe HCMV infections showed overlapping levels of total CD4+ T-cells, whereas determination of HCMV-specific CD4+ T-cells provided more targeted and reliable information for the management of HCMV infection complications." (PMID 25166270, 2014). "This raises the possibility that the effect of CMV infection on cfPWV is at least partly mediated by CD4 Tmem and observable in men but not women because upon CMV infection CD4 Tmem do not increase to the same extent in women as in men." (PMID 33897878, 2021). "An analysis of seven infants with congenital CMV infection showed a lack of production of IFN-γ, IL-2, and IL-4 from CD4+ T cells on exposure to pp65-derived peptide." (PMID 32509591, 2020). "We observed also that after reaching levels of both HCMV-specific CD4+ and CD8+ T cells similar to those found to be protective in immunocompetent subjects (>0,4 CD4+ and CD8+ T cells/μl blood) patients were able to control HCMV infection without need of antiviral treatment." (PMID 22848556, 2012).
type 2 diabetes (102 papers, 2007 to 2026). "Our previous study showed that CD4+ effector memory T cells are associated with lower immune function in aging and are associated with type 2 diabetes, which is itself proinflammatory." (PMID 38999941, 2024). "Advanced age, baseline CD4+ T-cell count <350/mm3, and type 2 diabetes were associated with transition from prefrailty to frailty." (PMID 38966850, 2024). "Two patients were associated with a new diagnosis of HIV with a CD4 count <100, four patients (13.3%) had diabetes mellitus type II, three patients (10%) were associated with alcohol consumption, and one case had renal insufficiency." (PMID 37275492, 2023). "Studies in animal models have found that certain types of T cells, such as CD6+ and CD4+, are moderately increased in patients with type 2 diabetes and are linked with proteinuria." (PMID 37554330, 2023). "Recently, altered microbiota dysbiosis has been linked to coronary heart disease, type 2 diabetes, and poor CD4 T-cell recovery." (PMID 30761121, 2018). "It was shown that the increased production of IL-10 by MSCs inhibited Th17 differentiation, an important proinflammatory CD4+ T cell subtype that is associated with type 2 diabetes." (PMID 30356025, 2018). "A higher degree of chronic adaptive immune activation, reflected by higher memory and lower naive CD4+ cells, was positively associated with type 2 diabetes." (PMID 26458065, 2015). "Our results identifying associations of higher memory and lower naive CD4+ T cells with type 2 diabetes is consistent with a role of chronic adaptive immune activation and exhaustion augmenting inflammation during the pathogenesis of type 2 diabetes." (PMID 26458065, 2015). "We have demonstrated that a higher degree of chronic adaptive immune activation, reflected by higher memory and lower naive CD4+ T cell proportions, was associated with prevalent type 2 diabetes in a population-based multi-ethnic cohort." (PMID 26458065, 2015). "In summary, higher memory and lower naive CD4+ T cells were associated with type 2 diabetes in a multi-ethnic population-based cohort." (PMID 26458065, 2015). "Apart from the innate immune system the adaptive immunity seems also to be implicated in the chronic inflammation of type II diabetes and CD4-positive T lymphocytes are the first cells to infiltrate fat tissue." (PMID 22104207, 2011). "There is also evidence that poorly controlled HbA1c (HbA1c 1-year mean > 7%) following SARS-CoV-2 vaccination in a cohort of patients with type 2 diabetes is associated with a reduced cytokine response from CD4+ T cells and increased incidence of breakthrough infections." (PMID 38214784, 2024). "Advanced age, baseline CD4+ T-cell count <350 cells/mm3, and type 2 diabetes were associated with transition from prefrailty to frailty (adjusted odds ratio [aOR], 1.10 per 1-year positive difference; 95% CI, 1.01–1.20; aOR, 3.05; 95% CI, 1.14–8.18; and aOR, 2.63; 95% CI, 1.05–6.57; respectively)." (PMID 38966850, 2024). "In the present study, older age and CD4+ T‐lymphocyte count lower than 200 cells/mm3 were associated with fibrosis and type 2 diabetes showed a trend towards statistical significance, whereas duration of HIV infection, cumulative use of ART and metabolic syndrome were not." (PMID 30394678, 2018). "Each standard deviation (SD) higher CD4+ memory cells was associated with a 21% higher odds of type 2 diabetes (95% CI: 1–47%) and each SD higher naive cells was associated with a 22% lower odds (95% CI: 4–36%) (adjusted for age, gender, race/ethnicity, and BMI)." (PMID 26458065, 2015). "We previously found that CD4+ regulatory T-cells (Tregs) are markedly reduced in type 2 diabetes (T2D) after ischemic injury in both mice and humans, and that Treg deficiency in immunodeficient mice impairs vascular regeneration." (PMID 42159401, 2026).
type 2 diabetes (continued). "In mouse models of type 1 and type 2 diabetes, it ameliorated insulin-related defects and appeared to modulate the pro-inflammatory profile of insulin-reactive CD4+ T cells." (PMID 40724942, 2025). "Independent contribution of type 2 diabetes to alterations in different CD4 T-helper cell subsets among TB patients, by multivariable analysis." (PMID 40995361, 2025). "The data presented above provide further evidence supporting the findings that both pDCs and CD4+ populations are dysfunctional in type 2 diabetes." (PMID 38094119, 2023). "In a 2015 study, it was found that Sitagliptin, a DPP-4 inhibitor, affected the subsets of circulating CD4 + T cells in patients with type 2 diabetes." (PMID 38065905, 2023). "Subsequently, we stimulated the CD4+ overnight with a high glucose and lipid mixture to replicate the conditions of type 2 diabetes." (PMID 38094119, 2023). "Within the BNT162b2-elicited S-reactive CD4+T cells, the proportions of CM and EM cells were largely comparable between HCs and participants with type 2 diabetes following both doses of vaccination." (PMID 36304475, 2022). "In contrast, among the CoronaVac vaccinees, only 60-80% of HCs had detectable circulating S-reactive CD4+T cells following S1 peptide stimulation, and this proportion further reduced to 24-36% in participants with type 2 diabetes." (PMID 36304475, 2022). "Similar changes in the percentage of Th1 cells was also detected in S2-reactive CD4+T cells from participants with type 2 diabetes." (PMID 36304475, 2022). "Increases in the percentage of S-reactive CD4+ TSCM cells were observed in participants with type 2 diabetes after their first dose of BNT162b2, but this difference was no longer observed after the second dose." (PMID 36304475, 2022). "Another study performed among type II diabetes patients found a significant reduction in the naïve pool in both CD4 + and CD8 + populations and a significant rise in TEM and TEFF populations of the CD4 + subset compared to age‐matched controls." (PMID 35858901, 2022). "Specifically, the proportion of CoronaVac vaccinees harbouring S1-reactive IFNγ+CD4+T cells was significantly reduced in participants with type 2 diabetes (p=0.02) after adjustment for BMI." (PMID 36304475, 2022). "Consistently, S-reactive CD4+T cells in participants with type 2 diabetes exhibited significantly lower expression of IFNγ, the defining cytokine for Th1 response following the first dose." (PMID 36304475, 2022). "Less reactivity to S2 peptide pools were observed in HCs, with only 40-50% showing positive CD4+T cell response and this rate remained similar in participants with type 2 diabetes." (PMID 36304475, 2022). "Consistent with a proinflammatory state, several key cell surface antigens (Cd4, Cd68, Cd84), immune sensors (Cx3cr1, Clec7a), and macrophage genes (Axl, Slc11a1) were upregulated in hIAPP islets and in type 2 diabetes." (PMID 34554282, 2022). "Although there is evidence of stenosis if T cells are engaged in the development of DN, limited animal experiments have found that CD6+ and CD4 + T cells are moderately increased in type 2 diabetes patients and are correlated with proteinuria." (PMID 34424825, 2021). "Elevated levels of CD4+ T cells which produce IL-17 (Th17 subset) in peripheral blood of patients with type 2 diabetes mellitus (T2DM) has been recognized as a major contributor to chronic inflammation in these individuals." (PMID 32039196, 2019). "We acknowledge that the relative low prevalence of patients with CD4+ T‐lymphocyte count <200 cells/mm3 and individuals with type 2 diabetes in the presence study sample should be taken into account when interpreting these results." (PMID 30394678, 2018). "While a declining trend of naïve CD4+T cells and imbalance of CD4+T cell subsets, including Treg, Th1, and Th17, have been observed in patients with type 2 diabetes." (PMID 30044774, 2018).
type 2 diabetes (continued). "Using sensitive immuno-markers of B and T lymphocytes, increased numbers of CD4, and particularly of CD 8 positive T cells, are demonstrated in both AD and type 2 diabetes, indicating a minimal involvement of the adaptive immune system." (PMID 26961231, 2016). "We evaluated the cross-sectional relationships of circulating NK cells, γδ T-cells, CD4+ naive T-cells, CD4+ memory T-cells, Th1, and Th2 cells with prevalent type 2 diabetes in 929 free-living participants of the Multi-Ethnic Study of Atherosclerosis (MESA)." (PMID 26458065, 2015). "The results can be summarized as follows: lower CD4 TRECs were significantly associated with higher past BMI, HbA1c, CRP, or diagnosis with type-2 diabetes or fatty liver." (PMID 24651652, 2014). "ODNR01 therefore improved type 2 diabetes by targeting CD4+ T cells and consequently M1-cell polarization in DIO mice or ob/ob mice." (PMID 23027613, 2012). "The finding that low CD4 count plus coma was a reasonably sensitive and specific feature for CM is unfortunate." (PMID 17493266, 2007). "Of any variable or combination, CD4 count < 100/μl plus coma provided the highest J score, positive predictive value (0.58), and positive likelihood ratio (3.8, 95% CI 1.9 – 7.3)." (PMID 17493266, 2007). "Unfortunately, India ink exhibited a disappointing 60% sensitivity, worse than a clinical determination based on low CD4 count plus coma, therefore we are left advocating for increased availability of cryptococcal antigen tests (including use on serum)." (PMID 17493266, 2007). "In patients with Type 2 diabetes, black tea consumption was associated with increased regulatory T cells (CD3+ CD4+ CD25+ FOXP3) and immunosuppressive CD3+ CD4+ IL-10+ cells, alongside reduced proinflammatory CD3+ CD4+ IL-17+ cells and Th1-associated CD3+ CD4+ IFN-γ+ cells." (PMID 40008375, 2025). "Furthermore, the study investigating the role of the CCL25/CCR9 axis in the pathogenesis of type 2 diabetes identified a key role of CCR9 in inducing glycose intolerance via inducing the infiltration of CD4+ T cells in the small intestine." (PMID 39411316, 2024). "We demonstrated the dysfunctionality of CD4+ and pDC populations in type 2 diabetes." (PMID 38094119, 2023). "Given the reliance of Th1 differentiation on glycolysis, the CD4+T cell defect in patients with type 2 diabetes could occur as a consequence of a reduction in glucose uptake." (PMID 36304475, 2022). "Factors independently associated with CKD diagnosis were older age, type 2 diabetes, gout and urolithiasis, which are known risk factors in the general population, receipt of TDF-containing regimens, and absolute CD4 cell count <200 cells/mm3, both being factors related to HIV infection." (PMID 36011147, 2022). "Positive CD4+T cell response was defined as the presence of TNFα and/or IFNγ production following peptide stimulation and similar responses were observed between participants with type 2 diabetes and HCs." (PMID 36304475, 2022). "Furthermore, among those with detectable S1-reactive CD4+T cell responses, the frequency of polyfunctional CD4+T cells which co-produced IFNγ and TNFα was also significantly lower in participants with type 2 diabetes (p=0.005)." (PMID 36304475, 2022). "However, among participants with type 2 diabetes, the proportion of S1-reactive CD4+T cells following the first dose was significantly lower compared with HCs, and this reduction was rectified after the second dose." (PMID 36304475, 2022). "However, a defect in the initial CD4+T cell response, exemplified by reductions in S-reactive CD4+T cells and Th1 differentiation, was found in patients with type 2 diabetes before their second dose of vaccination." (PMID 36304475, 2022). "In addition, the proportion of S-reactive CD4+T cells with cytotoxic potential (GZMB+CD107a+) was also comparable between participants with type 2 diabetes and HCs." (PMID 36304475, 2022).